SOX2 (SRY-box transcription factor 2)
Diseases named in the same sentence as SOX2 in open-access papers (continued):
Sharing a sentence is not in itself a finding about the gene and the disease.
tumor (continued). "Consequently, changes in other genes, which can counterbalance the growth inhibitory effects of elevated SOX2, enable SOX2 levels to rise during tumor progression." (PMID 32998722, 2020). "Since inhibiting EGFR activity promotes autophagic degradation of SOX2, we wondered whether the tumor inhibiting effect of gefitinib could be reversed by blocking autophagy." (PMID 31823521, 2020). "Importantly, our SOX2-inducible tumor studies provide a novel model system for investigating the molecular mechanisms by which elevated levels of SOX2 restrict cell proliferation and tumor growth." (PMID 32998722, 2020). "We show for the first time that elevating SOX2 in tumor cells representing four different tumor types decreases the expression of a broad spectrum of cell cycle machinery, in particular cyclins and CDKs that control the transition of each phase of the cell cycle." (PMID 32998722, 2020). "Moreover, Neu2-overexpressed tumor tissue samples showed reduction of pluripotent stem cells markers such as OCT4/SOX2/NANOG and PCS specific marker CD133 at the transcript level." (PMID 32575925, 2020). "Apart from the miR-449a, we have previously demonstrated that ICG-001 could also inhibit the growth of CSC-enriched NPC tumor spheroids via miR-145/SOX2 axis and the NPC cell migration via miR-150/CD44 axis." (PMID 32752071, 2020). "Patient tumor tissue samples demonstrated a partial, cellular colocalization of integrin α10β1 and Nestin (1‒10% of the integrin α10β1 cells), while fewer of the integrin α10-expressing cells also expressed Sox2." (PMID 31027305, 2019). "Oct4, Nanog, Sox2 and Bmi-1 are upregulated in PCa tissue and tumor-initiating PCa cells." (PMID 31238903, 2019). "These patient data demonstrate that the high SOX2 expression corresponds to poor survival, supporting our observation that Sox2+ SHH-MB cells may contribute to tumor recurrence." (PMID 31763624, 2019). "Thus, within the Sox2+ population, as with the broader tumor population, specific subsets of cells were relatively sensitive or resistant to vismodegib, and tumor-derived cells with stem cell-like transcriptomes persisted after vismodegib treatment." (PMID 31863004, 2019). "In addition, SOX2 overexpression subsequently increased the tumor incidence and the frequency of tumorigenic cells among both control and METTL3 knockdown SW620 cells." (PMID 31230592, 2019). "In addition, SOX2 silencing in GB tumor-initiating cells was shown to inhibit tumor proliferation, providing a potential treatment strategy for GB at the cellular level." (PMID 31683669, 2019). "This example of a context where RB-E2F transcriptional control may play a tumor suppressive role is particularly relevant because pituitary tumorigenesis in Rb1+/- mice is dependent on Sox2." (PMID 30703085, 2019). "However, the mechanisms underlying SOX2/OCT4 overexpression in CSCs are not fully understood, and the role of SOX2/OCT4 overexpressing cells in tumor initiation, progression and response to cancer therapies has not been well documented." (PMID 31500347, 2019). "In in vitro models, drug resistance induced by elevated HOTAIR expression may be caused by the promotion of tumor sphere cell growth and activation of tumor stem cell biomarkers such as Nanog, Oct3/4, Sox2, c-Myc, β-catenin, and Klf4." (PMID 31072041, 2019). "The spatial expression of MDK was closely correlated with that of SOX2 in a GBM tumor specimen." (PMID 31811117, 2019). "Importantly, circulating GFP+ tumor cells had significantly enhanced expression of Nanog, Sox2, and Oct4 (Oct4B and Oct4B1) compared with those directly injected into the mammary fat pads." (PMID 30651129, 2019). "Accordingly, over the same concentration range that inhibited LSD1 activity in vitro, oleacein treatment efficiently blocked the re-activation of SOX2 that is known to be controlled by the binding of LSD1 to the SOX2 distal enhancer differentially occurring in tumor cells with CSC-like properties." (PMID 31331073, 2019).
tumor (continued). "The differential expression of Sox2 was further retained in tumor-derived cell lines." (PMID 30723235, 2019). "Importantly, interrupting the TRIB3/AKT1 interaction by a modified α-helix peptide, Pep2–Ae, accelerated FOXO1 degradation, reduced SOX2 accumulation, and decreased the tumor-initiating capacity in MMTV-PyMT and PDX mice." (PMID 31844113, 2019). "To establish if our results could reflect a general link between SIX1 and SOX2 in cancer, we decided to investigate this connection in a different tumor type." (PMID 30723235, 2019). "Conversely, a lower percentage of SOX2-positive cells was observed in the NF1-knockdown tumor." (PMID 30967630, 2019). "SOX2 silencing through hypermethylation might promote tumor initiation by evading cell-cycle arrest in addition to resisting apoptosis." (PMID 30867047, 2019). "However, it should be noted that targeting tumor cells with an active OCT4/SOX2 promoter had a more potent effect than targeting those with an active CD133 promoter; probably due to the higher frequency of OCT4/SOX2 active cells in our GBM model." (PMID 31267022, 2019). "Overexpression of Sox2 leads to hyperplasia and tumor formation in several tissues." (PMID 31041783, 2019). "The analysis of tumors with SIX1 overexpression indicate that the oncogenic effect of SIX1 is associated with the repression of a senescent gene signature and the induction of a dedifferentiated tumor phenotype mediated, at least in part, by the stemness regulator Sox2." (PMID 30723235, 2019). "This trend was also evident in the primary tumor sections, and the difference was predominantly associated with the differential expression of PD‐L1 on Sox‐2‐expressing tumor cells, although this difference was also not significant (P = 0.6424)." (PMID 31929892, 2019). "Furthermore, a population of SHH-MB tumor-propagating cells expressing Sox2+ was described as the source of MB repopulating cells subsequent to therapy." (PMID 31700613, 2019). "In line with our findings, high expression of OCT4 and SOX2 has been associated with earlier stage, small tumor size, and the absence of lymph node metastasis, and high SOX2 expression was significantly associated with better disease-specific survival in OSCC." (PMID 31484317, 2019). "Tumor-initiating stem cells have been reported to potently express ObR, resulting in tumor progression mediated by the activation of STAT3 and induction of pluripotency-associated transcription factors, such as Oct4 and Sox2." (PMID 31141984, 2019). "Another explanation may be that SOX2 copy number gain and expression are early tumor-initiating events, but this gene can lose its relevance in conveying an aggressive or metastasizing phenotype." (PMID 31640140, 2019). "We next established a xenograft model in nude mice to address the role of SOX2 in tumor growth." (PMID 31560173, 2019). "FACT levels are enhanced in GSCs compared to bulk tumor cells, its expression decreases during differentiation, and FACT’s knockdown leads to a decrease in the expression of transcription factors associated with stemness such as Sox2, Oct4, Olig2, and Nanog." (PMID 31752169, 2019). "Although Sox2+ MB cells are tumor-propagating cells present in primary Shh-MBs, their origin and whether they are derived from ventricular NSCs are unknown." (PMID 31700613, 2019). "Overexpression of SOX2 in tumor cells is due to amplification of the gene at 3q26.33 region." (PMID 31508790, 2019). "Altogether, our data suggest that MTA3 is capable of repressing TSCC CSC properties and tumor growth through downregulating SOX2 and MTA3low/SOX2high might be a potential prognostic factor for TSCC patients." (PMID 31552166, 2019). "SOX2 expression has also been analyzed during tumor progression." (PMID 31640140, 2019). "SOX2 located at 3q26 has emerged as a candidate tumor driver gene within this locus." (PMID 30823625, 2019).
tumor (continued). "Interestingly, SOX2 and ST6GAL1 are located within the same tumor-associated amplicon, 3q26, and these two genes exhibit coordinate gains in copy number across multiple cancers including ~ 25% of ovarian serious adenocarcinomas." (PMID 31610800, 2019). "Loss of LATS1 is sufficient to drive deregulation of SOX2+ pituitary stem cells, generating highly proliferative non-functioning tumours with features of carcinomas." (PMID 30912742, 2019). "NRF2 and SOX2 TFs are key for tumor progression and inhibiting them effectively reduces metastasis." (PMID 30644396, 2019). "Notably, the level of SBSN expression was significantly higher in CTC and lung and liver metastases than in primary tumour and parental 4T1 cells, a feature that correlated with increased Sox2 expression in these cells." (PMID 30919591, 2019). "Interestingly, targeting SOX2 by RNA interference (RNAi) strongly affects tumor-initiating ability, as well as drug resistance, of CD133-positive GBM cells, suggesting a key role for SOX2 in the regulation of tumorigenicity in these cells." (PMID 30987226, 2019). "The SOX2 overlapping transcript (SOX2OT) may regulate the migration and invasion of multiple tumor cells and is related to susceptibility to various diseases." (PMID 31827385, 2019). "In addition, an inverse association between MEIS1 and SRY (sex determining region Y)‐box 2 (SOX2) in ESCC tumor samples was reported." (PMID 31090196, 2019). "Considering the role of Sox2 in pluripotency, it is probable that Sox2 may exert a role in stromal cells when tumor cells produce the tissue organ involving surrounding cancer stroma." (PMID 30518951, 2018). "Among tumor-associated immune cells, tumor-associated macrophages were found to promote CSC-like phenotypes through Milk Fat Globule-EGF Factor 8 (MGF-E8)/STAT3 and Sonic Hedgehog pathways, or through EGFR/STAT3/Sox2." (PMID 29588647, 2018). "Finally, a recent study on the activation of the MAPK/ERK pathway during pituitary development has provided evidence for a population of proliferative SOX2-expressing cells within human papillary craniopharyngioma (PCP) tumours." (PMID 28855316, 2018). "Interestingly, one patient experienced a prolonged progression free survival (27 months), with a tumor showing amplification of SOX2, a CSC-related gene." (PMID 29581874, 2018). "However, some studies have reported that SOX2 suppresses tumour formation and that SOX2 overexpression inhibits cell proliferation." (PMID 29374236, 2018). "Nevertheless, neither SOX2OT expression nor SOX2 expression was associated with ESCC tumor size, lymphatic metastasis, N stage, M stage and prognosis." (PMID 29849506, 2018). "In this context, we hypothesized that the expression of the transcription factor SOX2 might be modulated by pH variations of tumor extracellular microenvironment and have a role in this metabolic adaptation." (PMID 30466459, 2018). "SOX2 and TKNR2 amplifications are associated with high tumor burden." (PMID 30060526, 2018). "In addition, SOX2-expressing cells function as tumour propagating cells upon transplantation, while the removal of SOX2-postive cells from established tumours leads to regression." (PMID 29506506, 2018). "Our results thus far indicated that the loss of bona fide SOX2+ CSCs did not impact the tumor-initiating potential of HN120PCR cells, thereby suggesting a potential switch in stem cell hierarchy." (PMID 30467425, 2018). "Tumour initiation can be prevented by deletion of the Sox2 gene." (PMID 29506506, 2018).
tumor (continued). "This is consistent with the reduction of OCT4, NANOG and SOX2 expression, reduction in the BCSC population by loss of the ALDH1 and CD44+/CD24– population, the deformation of mammospheres, and the strong reduction in animal tumor volume and tumor weight." (PMID 30542507, 2018). "Moreover, the expression of SOX2 and its correlation to clinical outcome are highly variable among different tumor entities." (PMID 29596469, 2018). "Indeed, we observe that Sox2 is expressed mainly at the epithelial cells but it is occasionally expressed also in stromal cells in tumor lesions of Sox2 promoter responsive GFP mice (our unpublished observation, HY and KT)." (PMID 30518951, 2018). "Very importantly, a recent study showed that SOX2 could act as a master regulator of tumor squamous cell differentiation." (PMID 30060526, 2018). "Furthermore, HPV-positive tumours were detected in 30/298 (10.07%) patients and HPV-negative tumours were detected in 268/298 (89.93%) patients in the SOX2-low subgroup." (PMID 29374236, 2018). "It has been demonstrated that PAI-1 inhibitor could decrease the activity of the core promoter and enhancer of Sox2 gene in tumor-initiating stem cells (TICs) of head and neck cancer." (PMID 29991717, 2018). "Neither SOX2OT expression nor SOX2 expression was observed to be associated with ESCC tumor size, lymphatic metastasis and TNM stage." (PMID 29849506, 2018). "In GBM cells positive for CD133, silencing SOX2 impaired tumor initiation and drug resistance." (PMID 29849507, 2018). "However, recent studies support a more complex model in which the regulation and function of SOX2 during neoplastic transformation and malignant progression is highly context dependent and critically involved in tumor cell plasticity." (PMID 29596469, 2018). "Since tumors with a higher tumor stage seemed to undergo a loss of SOX2, we performed immunohistochemical analyses to measure proliferation with an anti-ki67-antibody in representative tumor samples with high, low and absent expression of SOX2." (PMID 29596469, 2018). "Andoniadouet al. created a mouse model that expresses degradation-resistant β-catenin in Sox2+ cells upon tamoxifen induction to determine whether these cells could give rise to tumours at the embryonic stage and also in adult mice." (PMID 28781761, 2017). "Although it is known that changes in SOX2 expression can negatively affect the ability of tumor cells to migrate and invade, our data show evidence of new relationship between CMV70-3P inhibition and SOX2 expression besides its regulation thorough transcription and p107." (PMID 27517625, 2017). "Importantly, we are not aware of any studies reporting that AKT inhibitors reduce the stability of SOX2 in tumor cells." (PMID 28388544, 2017). "Interestingly, HIF-1 α, which is involved in mediation of the hypoxic responses in the majority of cell types, is expressed in our tumor model along with SOX2 and OCT3/4." (PMID 28249000, 2017). "Moreover, cervical squamous cancer patients with high SOX2 expression in tumour cells have enhanced radiation resistance." (PMID 27343550, 2017). "SOX2-expressing cells could serve as the founding population responsible for tumor initiation, growth, and metastasis." (PMID 29296232, 2017). "In our study, we analyzed the data, with respect to stratification, based on tumor location and stage, we found that Sox2 had predictive value in cardiac gastric cancers or earlier stage (Stages I and II), but not in non-cardiac gastric cancers or later stage (Stages III and IV)." (PMID 28046028, 2017). "In this regard, blocking the expression or function of genes that enable elevated SOX2 levels to promote tumor growth could convert the action of SOX2 from a growth promoter (oncogene) to a growth inhibitor (tumor suppressor gene)." (PMID 28388544, 2017).
tumor (continued). "We additionally could prove a significant correlation between high amounts of Sox9 and the appearance of Sox2 positive cell clusters within the tumour surrounding brain tissue." (PMID 29158570, 2017). "Tumor growth and progression is driven by cancer stem cells that possess self-renewal ability, and the maintenance of CSCs is regulated by key embryonic stem cell transcription factors (i.e. SOX2, OCT4 and NANOG)." (PMID 28068409, 2017). "TLX, which is also induced by SOX2 in neurogenic areas, represses the expression of the tumor suppressing gene phosphatase and tensin homologue (PTEN) and various micro RNAs involved in cell differentiation, while promoting the expression of Wnt7a and other factors involved in NPC proliferation." (PMID 28493916, 2017). "It has been shown that SYT-SSX can interfere with assembly of BAF (BRG-/BRM-associated factor) complexes affecting the integration of a tumor suppressor component and consequent SRY (sex-determining region Y)-box 2 (SOX2) activation which stimulates cell proliferation." (PMID 28191313, 2017). "Interestingly, the expression level of SOX2, a stemness marker in cancer cells was upregulated in tumor tissues as compared to the normal tissues." (PMID 28460458, 2017). "In addition to miRs, several long non-coding RNAs (lncRNAs) have been reported to influence the levels of SOX2 in tumor cells." (PMID 28388544, 2017). "In addition, it was demonstrated that miRNA-625-3p negatively regulates Sox2, which promotes tumor invasion and metastasis by stimulating EMT via regulation of WNT/β-catenin, and tumor growth via AKT/MTOR signaling pathways." (PMID 28863773, 2017). "Going forward, it will be important to determine whether the SCR, which is active in ESC, is also active in other SOX2-expressing cells, in particular SOX2-positive tumor cells." (PMID 28388544, 2017). "Thus, for several cancers, there is a need to more carefully determine how SOX2 levels change during tumor progression." (PMID 28388544, 2017). "If SOX2 is required for the tumor-initiating/cancer stem cell population, which is the case for at least some cancers, SOX2 levels may rise as the population of TIC increases during tumor progression." (PMID 28388544, 2017). "As a large body of published studies demonstrates a correlation between high expression levels and poor prognosis, an elevated incidence of recurrence, and/or invasive and metastatic capacity of tumor cells, SOX2 has been considered as a potential therapeutic drug target." (PMID 28671620, 2017). "The results indicated that Sox2 might promote tumor cell migration and invasion into blood vessels, and eventually facilitate metastasis to the liver." (PMID 29228716, 2017). "Aberrant activation of Sox2 in tumor cells might provide this specificity for cancer stem cell‐targeted drug screening." (PMID 28191771, 2017). "In the future, defining the roles of each of the SOX2 modifications and the enzymes involved in tumor cells may provide valuable insights into possible strategies for targeting SOX2 in a large number of cancers." (PMID 28388544, 2017). "Therefore, obliterating SOX2 expression specifically in brCSCs before or during chemotherapy is a possible approach to eliminate the brCSC population within a tumor, with a promise to prevent post-chemotherapy recurrences in future." (PMID 28835684, 2017). "In addition, downregulation of the stem cell genes Nanog, Oct3/4 and Sox2 were consistently observed in the mice tumours, NSCLC cells and biopsies." (PMID 29072692, 2017). "These liposomes should have a shell coated with aptamers or antibodies specific for CSC markers such as CD133, and would carry antitumor antibiotics (doxorubicin) or genome editing tools that would modulate the expression of genes important for tumor survival, such as SOX-2." (PMID 28408882, 2017).